IL1B (interleukin 1 beta)
Diseases named in the same sentence as IL1B in open-access papers (continued):
Sharing a sentence is not in itself a finding about the gene and the disease.
tumor (continued). "IL-1β was significantly elevated in the MPR group (9.18 ± 3.42 vs. 1.84 ± 2.26, P = 0.021), potentially indicating a more active proinflammatory state associated with effective tumor clearance." (PMID 41601630, 2026). "This suggests that PRMT1 may regulate IL-1β expression, thereby promoting tumor stemness and immune suppression in TNBC, which in turn sustains chemoresistance." (PMID 40927753, 2025). "However, NLRP3 inflammasome is activated by a tumor-derived signal in the immune cells that cleaves pro-IL-1β to active IL-1β by caspase-1 and finally promotes thrombosis in the IL-1β/NLRP3 pathway." (PMID 39857281, 2025). "Like macrophages, following stimulation by tumor-derived cytokines including IL-1β, IFN-β, TGF-β, IL-8, and prostaglandin E2 (PGE2), TANs acquire the potential to be polarized to either the antitumor N1 (mainly IFN-β induced) or protumor N2 (mainly TGF-β induced) phenotype." (PMID 40805183, 2025). "Furthermore, ALDH3A2-induced ferroptosis promotes an anti-tumor immune microenvironment via M1 macrophage polarization and IL-1β-mediated PD-L1 downregulation." (PMID 41444219, 2025). "Furthermore, P. gingivalis recruits myeloid cells, alters the tumor microenvironment, and increases the production of pro-inflammatory cytokines, such as TNF-α, IL-6, and IL-1β, thereby further driving tumor growth." (PMID 41473772, 2025). "Additionally, pectin, particularly MCP, has been shown to decrease the levels of proinflammatory cytokines such as IL-6, TNF-α and IL-1β, which are often elevated in the tumor microenvironment and contribute to tumor progression." (PMID 41249064, 2025). "For instance, bortezomib, a drug that interferes with protein breakdown, can suppress tumor survival signals, while cytokine blockers such as canakinumab (which targets IL-1β) and tocilizumab (which targets IL-6) have shown the potential to lower cancer risk and improve response to therapy." (PMID 41514860, 2025). "Notably, IL-1β is upregulated during GPX4-deficient Treg ferroptosis, which subsequently activates DCs and CD8 + T cells, leading to suppressed tumor growth." (PMID 41326356, 2025). "Therefore, the Lumit Human IL-1β Immunoassay was used to determine the concentration of IL-1β released into the culture media by normal and tumor cells in contact with the proposed GF-based scaffolds." (PMID 39940603, 2025). "On the other hand, TGF-β, TNF, IL-1β promote tumor cell proliferation." (PMID 41333471, 2025). "Based on these findings, we hypothesize that chronic exposure to HDM and subsequent activation of the IL-1β signaling pathway change lung microenvironment and make it conducive to tumor growth." (PMID 41445736, 2025). "Phytic acid reduces the expression of pro-inflammatory markers such as cyclooxygenase 2 (COX-2), inducible nitric oxide synthase (iNOS), interleukin-1 beta (IL-1β), interleukin-6 (IL-6), and interleukin-10 (IL-10), creating a less favorable environment for tumor growth." (PMID 39942108, 2025). "In cancer, IL-1β, IL-4 and IL-6 are well-known for their tumor promoting effects, including enhancing tumor cell proliferation and survival, supporting cancer cell stemness, and facilitating invasion and angiogenesis through autocrine signaling or crosstalk with tumor infiltrating immune cells." (PMID 40108668, 2025). "In terms of inflammatory factors, IL6, IL1B, and NFKB1 expression levels were notably reduced in the combination treatment group relative to the control group, suggesting a potential reduction in tumor-associated inflammation." (PMID 40361560, 2025). "Furthermore, MSCs' high proliferative capacity and tumor-homing potential enable recruitment into tumor microenvironments in response to hypoxia or pro-inflammatory cytokines (e.g., IL-1β, TNF-α, IFN-γ)." (PMID 41169880, 2025).
tumor (continued). "Specifically, the inhibition rates for IL-1β were 10.79 ± 0.45% and 23.25 ± 0.29% in serum, 4.50 ± 1.52% and 19.92 ± 1.03% in liver tissue, 7.20 ± 0.18% and 18.26 ± 1.09% in spleen tissue, and 0.64 ± 0.60% and 18.43 ± 1.02% in tumor tissue." (PMID 40429988, 2025). "Noteworthy, the overall consequences of inflammasome activation and IL-1β release following chemotherapeutic treatment may vary with the stage of the tumor." (PMID 39857785, 2025). "Similarly, in breast cancer research, inflammasomes and IL‐1β were found to promote tumor growth and migration." (PMID 40671967, 2025). "When engaged predominantly on TAMs and MDSCs, and triggered by ligands such as Galectin-9 or tumor-associated β-glucans, Dectin-1 signaling drives immunosuppressive reprogramming, leading to PGE2 and IL-1β production, T cell dysfunction, and resistance to checkpoint blockade." (PMID 41163402, 2025). "ELISA further confirmed a reduction of pro‐inflammatory cytokines TNF‐α and IL‐1β in tumor tissues." (PMID 41200213, 2025). "When it came to TDEs in the stress and propranolol co‐treated group (vivo S+P‐exo), this increase was inhibited, indicating that the elevated IL‐1β secretion by neutrophils influenced by chronic stress‐induced TDEs was attributed to the activation of β‐adrenergic receptors on tumor cells." (PMID 39630109, 2025). "TNF-α, IL-1β, and iNOS are inflammatory cytokines that are secreted by M1 macrophages and can eliminate infectious organisms such as bacteria, viruses, and malignant tumor cells, then macrophages phagocytose cells that are dead." (PMID 39775258, 2025). "Moreover, recent evidence suggests that IL-1β, despite being a classical pro-inflammatory cytokine, can also contribute to immune suppression within the tumor microenvironment independently of inflammasome activation." (PMID 41003874, 2025). "Preclinical studies using renal cell carcinoma mouse models further revealed that combinations of IL-1β inhibitors with anti-PD-1 antibodies or tyrosine kinase inhibitors yielded significantly enhanced anti-tumor responses compared to monotherapeutic approaches." (PMID 40563367, 2025). "We speculate that LAG3 may regulate inflammatory vesicle activation via IL‐1β feedback, a pathway that warrants further investigation in the future given the dual role of IL‐1β in tumor promotion and suppression." (PMID 41025546, 2025). "Overall, IL-1β may function by affecting tumor-specific Th1 cells, macrophages, or tumor cells in the tumor microenvironment." (PMID 40244135, 2025). "Finally, the alliance of CAR-Ts with CAR-Ms remodulates the TME to the detriment of the tumour via a large cytokine network including IL-6, IL-1β, and IFN-γ." (PMID 40574837, 2025). "In immunosuppressive conditions, excessive expression of IL-1β downstream of NLRP3 activation may promote tumor progression by exacerbating chronic inflammation and facilitating immune evasion." (PMID 40718836, 2025). "Moreover, the secretion of IL-1β can recruit immunosuppressive cells, such as regulatory T cells and M2 macrophages, that can inhibit the anti-tumor immune response, and promote angiogenesis and matrix remodeling, providing tumor progression." (PMID 41560727, 2025). "Therefore, curcumin reduces tissue damage and chronic inflammation by inhibiting activity of IL1B, thereby affecting tumor microenvironment." (PMID 40535567, 2025). "Furthermore, CD8+ cytotoxic T cells are required to inhibit tumor progression and are critical drivers of CD4+ T cell and TAM activation in IL-1β-deficient mice." (PMID 39858071, 2025).
tumor (continued). "For instance, TGF-β and IL-1β secreted by senescent CAFs can induce tumor cell senescence while enhancing their invasiveness and chemotherapy resistance.Notably, therapeutic strategies targeting CAFs and cellular senescence are emerging as new directions in cancer treatment." (PMID 40755775, 2025). "Among these factors, IL-1β plays a contradictory role in tumor development." (PMID 40244135, 2025). "Furthermore, combining PD1/PD-L1 inhibition with IL-1β inhibition produced synergistic effects: in preclinical studies, anti-IL-1β antibodies combined with PD-1 blockade completely halted tumor progression." (PMID 40868199, 2025). "One such reported case is colorectal cancer invasion that could be affected by tumor-derived IL-1β, which induces the expression of human SAA1." (PMID 39940756, 2025). "This approach may work because inflammasome activation can trigger pyroptosis in cancer cells, releasing pro-inflammatory cytokines such as IL-1β and IL-18 that can aid in anti-tumor immune responses." (PMID 40141358, 2025). "On one hand, inflammasomes such as NLRP3 and AIM2 can suppress tumorigenesis by enhancing anti-tumor immunity through the activation of caspase-1 and subsequent maturation and release of pro-inflammatory cytokines like IL-1β and IL-18, which recruit and activate immune cells." (PMID 40692785, 2025). "In addition, TNF-α, IL-1β, and IL-6 have been demonstrated to suppress cell mediated immunity and promote intravascular tumor cell adhesion." (PMID 40427164, 2025). "Second, it drives M1 macrophage polarization to suppress CRC: In CT26 tumor-bearing mice, intraperitoneal inosine (5–50 mg/kg/day) dose-dependently upregulates M1 markers and reduces M2 markers, with 50 mg/kg achieving 47.39% tumor inhibition via NF-κB/IL-1β activation." (PMID 41181090, 2025). "In addition, CAF-derived IL-1β initiates transcriptional upregulation of the chemokine CCL22 in tumor cells through NF-κB activation, thereby facilitating regulatory T cell (Treg) recruitment and reinforcing local immune suppression." (PMID 41583435, 2025). "Additionally, IL-1β is pivotal in facilitating cancer progression by promoting metastasis, angiogenesis, and tumor development." (PMID 40100373, 2025). "Furthermore, technological advances in single-cell and spatial transcriptomics have enabled precise characterization of the role and mechanisms of IL-1β within tumor tissues." (PMID 40948749, 2025). "IL-1β, the primary form of IL-1, is involved in various autoimmune inflammatory responses and cellular activities, including cell proliferation, differentiation, apoptosis, inflammation, autoimmunity, and tumor development." (PMID 40536724, 2025). "Besides, it is reported that B cells recruited by tumor cells can activate IL-1β/HIF-2α signaling and induce the downstream Notch1 signaling pathway, significantly increasing the migration and invasion of RCC cells." (PMID 39744696, 2025). "Ongoing translational research from this study, as well as from other CANOPY studies, may help characterize the effects of IL-1β inhibition in the tumor microenvironment and identify whether any subgroup may benefit from this treatment." (PMID 40810132, 2025). "In addition, NLRP3 activation in neutrophils induces IL-1β and IL-18 secretion, promotes chronic inflammation and enhances tumor growth." (PMID 41157253, 2025). "However, GPX4 deletion in Tregs can activate ferroptosis, promote IL-1β production, and enhance Th17 cell responses, thereby enhancing antitumor immunity and inhibiting tumor growth." (PMID 40760119, 2025). "Cytokines, such as IL-1β and IL-8, stimulate tumor proliferation." (PMID 40430101, 2025). "Recent studies have shown that IL-1β plays an important role in tumor metastasis." (PMID 40593461, 2025). "These IL-1β+ TAMs, enriched in hypoxic regions of the tumor, further promote PDAC progression." (PMID 41243973, 2025).
tumor (continued). "Notably, IL-1β appears to suppress anti-tumor immunity, and removing IL-1β unleashes a more effective T-cell response." (PMID 41007766, 2025). "Interestingly, in the mice model, antibody-mediated neutralization of IL1β significantly enhanced the antitumor activity of α-PD-1 and was accompanied by increased tumor infiltration of CD8+ T cells." (PMID 41228323, 2025). "The presence of micrometastatic tumor cells in the liver may also activate Kupffer cells to produce a variety of cytokines (IL-1b, IL-6, TNF), which regulate albumin synthesis by hepatocytes." (PMID 40004975, 2025). "They promote the generation of IL-1β and IL-23 by myeloid cells, and then induce proliferation of γδ T cells that facilitate formation of IL-17 and other inflammatory molecules, leading to inflammation that exacerbates tumor progression." (PMID 39995663, 2025). "Notably, IL-1β can induce IL-6 production, a cytokine known to promote tumor progression via STAT3 activation." (PMID 41445736, 2025). "Future studies could incorporate H. pylori status or measure additional cytokines (like IL-1β, IL-6) to dissect the contributions of tumor versus background inflammation." (PMID 40299527, 2025). "M-I treatment of TNBC cells and tumor-bearing mice significantly reduced IL-1β expression." (PMID 40723226, 2025). "Particularly, Canakinumab, a fully human monoclonal antibody against IL-1β, in combination with Pembrolizumab anti-PD-1 antibody delayed tumor growth and increased infiltration of CD8 T cells in a humanized bone marrow liver thymic non-small cell lung cancer model." (PMID 39948655, 2025). "In this study, 24 h after central nervous system (CNS) ischemia, the concomitant inflammatory cascade response with elevated levels of tumor necrosis caused systemic peaks of TNF-α, IL-1β, and IL-6, and pre-administration of GJC-CDs reduced the levels of related inflammatory factors." (PMID 40573265, 2025). "We hypothesized that the Toe-Macs in NSCLC are pathogenic, in part due to enhanced expression of the key tumor-promoting factors NLRP3, IL-1β, TGF-β1, CCL2, IL-6, and PD-L1 (encoded by CD274)." (PMID 40794443, 2025). "It has also been shown that both IL-1α and IL-1β may help with tumor angiogenesis and invasiveness as PCa develops, as stated in a review by Ullah, Jiao, and Shen." (PMID 40427694, 2025). "Interestingly, the results showed that A. sydowii promoted tumor progression via IL-1β-mediated expansion and the activation of MDSCs, resulting in suppressed activity of cytotoxic T-cells and an accumulation of PD-1+ CD8+ T-cells." (PMID 40985415, 2025). "Furthermore, IL1RAP enhances inflammatory responses in the tumor microenvironment by mediating the pro-inflammatory effects of IL-1β, thereby supporting tumor growth and invasion." (PMID 40444099, 2025). "Both the size and number of U87 tumor spheres were increased significantly in IL-1β treated plates." (PMID 40725140, 2025). "Notably, inhibition of HDAC6 with Tubastatin A markedly slowed tumour growth, lowered IL-1β levels, and shifted the immune landscape toward an anti-tumour profile; reducing M2 macrophages while enhancing M1 macrophage responses." (PMID 41440367, 2025). "Previous reports proposed IL-1β mainly secreted by immune cells in tumor microenvironment could support tumor growth." (PMID 41145465, 2025). "By attenuating IL-1β, IL-6, IL-8 and related chemokines, statins may weaken the inflammatory pathways that sustain tumour growth and immune evasion in cancer and strengthen the efficacy of therapeutic regimens in cancer patients." (PMID 40943351, 2025). "A PRX4-overexpressed transgenic mouse model revealed that reduced oxidative stress through overexpressed PRX4 promotes cancer development, such as with highly penetrated microvessels in tumors; upregulated cytokine levels, including IL-1β and matrix metallopeptidase 9; and enhanced tumor size." (PMID 40722961, 2025).
tumor (continued). "Additionally, when co-cultured with tumor cells, BBζ-Neo exhibited higher levels of IFNγ, IL-1β, IL-6, MCP-1, TNF-α and IL-8 compared to BBζ." (PMID 40025022, 2025). "In addition to GSDME-mediated pyroptosis, the Cu-TBB nanomedicine releases Cu+ to generate ROS with O2 as a substrate in tumor cells, activating caspase-1-mediated classical pyroptosis via Gasdermin-D cleavage and promoting release of IL-1β, IL-18, and DAMPs." (PMID 40717985, 2025). "However, when intermediate monocytes are activated via C5a, they secrete IL-1β and facilitate tumor cell proliferation, migration, and epithelial-to-mesenchymal transition (EMT), while reducing tumor cell apoptosis." (PMID 41440002, 2025). "Conversely, in CRC liver metastases, HNSCC, and NPC, NLRP3 plays a significant role in promoting immune surveillance, boosting NK cytotoxicity, reshaping the anti-tumor response, and preventing local relapse through IL-1β-driven recruitment of anti-tumor neutrophils." (PMID 40155968, 2025). "Moreover, tumor cells produce IL-1β, CCL, VEGF, and SDF-1α, which recruit macrophages to the TME, facilitating inflammation, angiogenesis, and tumor growth." (PMID 40670983, 2025). "Furthermore, microcalcifications can recruit tumor macrophages (TAMs) that release osteogenic and pro-inflammatory factors (e.g., IL-1β), promoting tumor invasiveness." (PMID 40725750, 2025). "As a cancer-promoting factor, IL-1β promotes tumor immune escape by interacting with stromal cells." (PMID 40948749, 2025). "These molecules were demonstrated to modulate the production of pro-inflammatory cytokines, decreasing TNF-α and IL-1β release and increasing anti-inflammatory cytokine interleukin-10 (IL-10) by mouse peritoneal cells, lyse human tumor-derived cells, and mouse erythrocytes." (PMID 41003528, 2025). "In detail, the microbes may stimulate MyD88-dependent myeloid cells to produce IL-1β and IL-23, activating Vγ6+ Vδ1+ γδT cells to produce factors such as IL-17, leading to inflammation and tumor cell proliferation." (PMID 40185720, 2025). "Similarly, anti-IL-1β monoclonal antibody significantly enhanced the anti-tumor activity of anti-PD-1 antibodies in a preclinical model of PDAC, which was accompanied by increased infiltration of CD8 T cells into the tumor." (PMID 39948655, 2025). "In addition, IL-1β expression was evaluated using bulk RNA sequencing, which cannot distinguish between tumor cells and other immune or stromal populations in the TME." (PMID 40940992, 2025). "Finally, we assessed cytokine production at the protein level by immunofluorescent staining of frozen tumor sections for IL1β, IFNβ, and TNFα." (PMID 41401057, 2025). "Notably, TNF-α exhibits cytotoxic effects on tumor cells and also stimulates the secretion of IL-1β and IL-6." (PMID 40559782, 2025). "These microbial-metabolic perturbations synergistically activate NF-κB and STAT3 signaling pathways, generating a pro-inflammatory cytokine milieu (IL-6, TNF-α, IL-1β) that establishes a tumor-promoting microenvironment through autocrine and paracrine cascades." (PMID 40919140, 2025). "When tumor-bearing mice develop LC, the lesions themselves become a source of IL-1α and IL-1β." (PMID 41179937, 2025). "To further validate our transcriptomic findings, we assessed the protein expression levels of TNF-α and IL-1β—two cytokines that showed statistically significant differences in gene expression—using Western blot and immunohistochemistry (IHC) in tumor tissue samples." (PMID 40565357, 2025). "Thus, the presence of IL-1β can promote tumor progression, migration, and metastases by inducing EMT in cancer." (PMID 39858071, 2025).